RGL2 (ral guanine nucleotide dissociation stimulator like 2)
Description:
Probable guanine nucleotide exchange factor. Putative effector of Ras and/or Rap. Associates with the GTP-bound form of Rap 1A and H-Ras in vitro (By similarity).
Synonyms: RAB2L; KE1.5; HKE1.5
Tractability: Small molecule: a structure with a bound ligand is known. PROTAC: ubiquitination databases record sites on it; its protein half-life has been measured.
Gene: Protein-coding gene on chromosome 6 (33,291,196 to 33,299,419, reverse strand). Ensembl gene ENSG00000237441.
Subcellular location (Human Protein Atlas): Nucleoplasm
Pathways (Reactome):
Signal Transduction: RAF/MAP kinase cascade
Gene Ontology:
Molecular function: protein binding; guanyl-nucleotide exchange factor activity
Biological process: Ras protein signal transduction; signal transduction; small GTPase-mediated signal transduction
Cellular component: cytosol
Genetic constraint (gnomAD): Loss-of-function variants: 38 observed, 78.69 expected, observed/expected ratio (o/e) 0.48, 90% interval 0.37 to 0.63. The upper end of that interval is the gene's LOEUF score, 0.63, which puts it in group 2 of 6, group 1 being the genes least tolerant of losing a copy. Missense variants: 842 observed, 998.28 expected, observed/expected ratio (o/e) 0.84, 90% interval 0.8 to 0.89. Synonymous variants: 355 observed, 408.96 expected, observed/expected ratio (o/e) 0.87, 90% interval 0.8 to 0.95.
Homologues: Orthologues: chimpanzee RGL2 (99% identical), macaque RGL2 (98% identical), rabbit RGL2 (93% identical), mouse Rgl2 (90% identical), pig RGL2 (90% identical), rat Ralgdsl2 (88% identical), dog RGL2 (88% identical), guinea pig RGL2 (86% identical). Paralogues in human: RALGDS (35% identical), RGL3 (33% identical), RGL1 (31% identical), RAPGEF2 (17% identical), RAPGEF6 (15% identical), RAPGEF1 (15% identical), RGL4 (14% identical), SOS1 (13% identical), RASGRP1 (13% identical), RASGRP4 (13% identical), RASGRF2 (12% identical), RASGRP3 (12% identical), and 12 more.
Diseases named in the same sentence as RGL2 in open-access papers:
RGL2 is named in the same sentence as 20 diseases in open-access papers, as found by Europe PMC text mining. Sharing a sentence is not in itself a finding about the gene and the disease. The quoted sentences say what the papers report.
colorectal cancer (2 papers, 2021 to 2023). A primary or metastatic malignant neoplasm that affects the colon or rectum. "A recent study reported that RGL2 could drive the metastatic progression of colorectal cancer via preventing the degradation of β-Catenin and KRAS." (PMID 37237274, 2023). "We first analyzed the transcriptional profiling of RGL subtypes RGL1, RGL2, RGL3, and RGL4 in The Cancer Genome Atlas (TCGA) colorectal cancer (CRC) database." (PMID 33917100, 2021).
Obesity (2 papers, 2023 to 2024). Accumulation of substantial excess body fat. "We also observe a positive correlation of expression of the RalGEF RGL2 with BMI in adipose tissue of humans with obesity, expected to correspond to a chronic increase in RalA activity." (PMID 37398165, 2023).
atherosclerosis (1 paper, 2016). A disease characterized by the build-up of fatty material and calcium deposition in the arterial wall resulting in partial or complete occlusion of the arterial lumen. "Furthermore, previous results implicate RGL2 in atherosclerosis pathogenesis." (PMID 27884142, 2016).
bladder cancer (1 paper, 2024). "Furthermore, in vivo interaction of Rgl2 and Ras was reported in a BioID-based proteomics study where Rgl2 was among other proximal interactors identified using HRas.G12V expressed in bladder cancer cells." (PMID 37833074, 2024).
breast carcinoma (1 paper, 2021). "The data showed that RGL2 upregulation significantly (p < 0.05) correlated with an increased hazard ratio in the enrolled CRC cohorts, as well as two cohorts with blood and breast cancer." (PMID 33917100, 2021).
fibromyalgia (1 paper, 2014). A chronic disorder of unknown etiology characterized by pain, stiffness, and tenderness in the muscles of neck, shoulders, back, hips, arms, and legs. "Fibromyalgia has been genetically linked to the HLA region (6p21.3) 63, which includes several genes associated with Notch signalling (e.g. Notch4, FKBP5, TNXB, MTCH1 and TNF-a) or with stem cell maintenance and proliferation (e.g. POU5F1, Flot1, MAPK14, Rgl2 and Rab44)." (PMID 25164209, 2014).
lymph node metastasis (1 paper, 2021). "The data showed that RGL2 upregulation highly correlated with the progression of lymph node metastasis in CRC patients." (PMID 33917100, 2021).
pancreatic cancer (1 paper, 2024). "Increased Ral activity has also been shown in KRAS-4B G12V-mutant pancreatic cancer, due to altered binding kinetics and a more dynamic interaction between KRAS-4B G12V and the RalGEF Rgl2, compared to the KRAS WT interaction with Rgl2." (PMID 39372214, 2024).
pancreatic ductal adenocarcinoma (1 paper, 2021). An infiltrating adenocarcinoma that arises from the epithelial cells of the pancreas. "A previous study observed the upregulation of RGL2 expression in the tumor tissue and cell lines of pancreatic ductal adenocarcinoma (PDAC)." (PMID 33917100, 2021). "In KRAS mutant pancreatic ductal adenocarcinoma (PDAC), an increased level of RGL2 was detected in tumors compared to normal tissues and was associated with PDAC metastatic capacity." (PMID 33917100, 2021).
cancer (3 papers, 2018 to 2024). A tumor composed of atypical neoplastic, often pleomorphic cells that invade other tissues. "To evaluate the clinical relevance of RGL2, we next performed a meta-analysis of RGL2 transcripts against patients with different cancer types in the PrognoScan database." (PMID 33917100, 2021). "It is important to examine whether the KRASG12X/+ cell lines’ cancer-related phenotypes depend on the RalA/B function and how Rgl2 and RalA/B status are altered in these cell lines." (PMID 38796063, 2024). "This study is the first to document the oncogenic role of RGL2 in promoting cancer progression." (PMID 33917100, 2021). "Although the cross-talk between β-catenin and KRAS has been reported to promote cancer metastasis, the functional role of RGL2 remains largely unknown." (PMID 33917100, 2021).
tumor (3 papers, 2021 to 2023). "We found that most genes with hazard ratio > 1 (GPRASP1, APLP1, ALPK3, SPTBN5, PCDHB14, LZTS3 and RGL2) have a higher expression in tumor tissues than normal tissues except LINGO1 and LZTS1." (PMID 37237274, 2023). "Protein level of tumor promoting genes (GPRASP1, APLP1, ALPK3, SPTBN5, PCDHB14, LZTS3, RGL2) were higher in tumor tissues." (PMID 37237274, 2023).
heart disease (1 paper, 2013). "Taken further, these results suggest that Rgl2 upregulation in hypertrophic hearts may be a protetive mechanism, and that Rgl2 may be a novel therapeutic target in treating heart disease." (PMID 24069211, 2013). "Future studies will examine the contribution of RalA-dependent and RalA-independent signaling pathways in Rgl2-induced activation of the PI3K/Akt signaling cascade, and whether Rgl2 represents a novel therapeutic target in cardiac disease." (PMID 24069211, 2013).
infection (1 paper, 2013). The state of being infected such as from the introduction of a foreign agent such as serum, vaccine, antigenic substance or organism. "In both cardiomyocyte model systems, infection with adenovirus encoding Rgl2 increased PI3K activity and decreased staurosporine-induced apoptosis, as assessed by decreased PARP and/or caspase-3 cleavage." (PMID 24069211, 2013). "Compared to AdNull-infected cells, infection of NRVMs or HL-1 cells with AdRgl2 increased Rgl2 protein expression." (PMID 24069211, 2013).
RGL2 also shares sentences with these, for which no sentence is quoted: babesiosis (1 paper); cardiac hypertrophy (1); fibrosis (1); non-small cell lung carcinoma (1); rheumatoid arthritis (1); Sepsis (1); type 1 diabetes (1).